ICAM1 (intercellular adhesion molecule 1)
Diseases named in the same sentence as ICAM1 in open-access papers (continued):
Sharing a sentence is not in itself a finding about the gene and the disease.
cerebral malaria (67 papers, 2007 to 2025). A sequestration of Plasmodium falciparum in the brain, which can cause coma and/or seizures. "Immunohistochemical analysis revealed that m8∆/AAV1 or RTS,S vaccination significantly reduced the expression of ICAM-1 in the brain vasculature, a marker often associated with cerebral malaria pathology." (PMID 39460322, 2024). "Cerebral malaria and severe malaria syndromes were associated previously with sequestration of IE to a microvasculature receptor ICAM-1." (PMID 34073419, 2021). "PfEMP1 containing DC13-variants are capable of binding to both the EPCR and ICAM-1, where both are implicated in cerebral malaria." (PMID 32153634, 2020). "ICAM-1 mediated IE cytoadhesion is known to be mediated by a subset of PfEMP1 and has been shown to be associated with cerebral malaria." (PMID 24674301, 2014). "It is also possible that HIV-infected children are at increased risk of developing cerebral malaria because of an increased production of nitric oxide synthase, ICAM-1 and VCAM-1 with HIV infection." (PMID 21235797, 2011). "ICAM1 is expressed at high levels in brains of patients with cerebral malaria, and has been implicated in this syndrome." (PMID 19381252, 2009). "Plasmodium falciparum–infected erythrocytes bind endothelial receptors to sequester in vascular beds, and binding to ICAM1 has been implicated in cerebral malaria." (PMID 19381252, 2009). "PE bind endothelial receptors to sequester in vascular beds, and PE binding to ICAM1 has been implicated in cerebral malaria." (PMID 19381252, 2009). "Importantly, the nanoparticles were functionalagainst two different parasite strains, a CSA-binder and an ICAM-1-binder,which are associated with placental malaria and cerebral malaria,respectively." (PMID 38271991, 2024). "Although they did not examine the regulatory relationship or leukocyte binding, there is evidence of IRF1 promoting ICAM-1-mediated leukocyte-endothelial cell interactions in other experimental systems, for example, cerebral malaria in Irf1 gene-deficient mice." (PMID 36834715, 2023). "DBLβ5 from group B var genes and specific motifs in DBLβ1 and DBLβ3 from group A var genes bind intercellular adhesion molecule 1 (ICAM1), and cerebral malaria has been associated with ICAM1 binding and expression of group A carrying tandem CIDRα1-DBLβ1/3 domains." (PMID 29529020, 2018). "While it has been speculated that receptor-specific adhesion (e.g. ICAM-1) predisposes to a particular pattern of disease (e.g. cerebral malaria), studies to date have been inconclusive." (PMID 24691798, 2014). "P. falciparum cytoadherence to ICAM-1 is associated with cerebral malaria." (PMID 24098393, 2013). "Importantly, high density parasite binding to ICAM-1 under flow conditions was significantly associated with cerebral malaria." (PMID 21390226, 2011). "ICAM-1 is of interest as it has been linked to cerebral malaria." (PMID 19800372, 2010). "Examination of brain tissue from patients who died with cerebral malaria has demonstrated adhesion of parasitized red cells, platelets, and leukocytes to brain endothelium in association with increased endothelial expression of ICAM-1." (PMID 20712868, 2010). "However, based on the antibody features identified using systems serology, we were able to hypothesize and confirm that ADNP of ICAM-1 + EPCR binding IE is associated with protection from cerebral malaria." (PMID 39267089, 2024). "In contrast, ADNP of ICAM-1 + CD36 binding IE (that contain DBLβ3_IT4VAR13) was elevated in cerebral malaria." (PMID 39267089, 2024). "In a recent study, CIDRα-DBLβ1/3 domains predicted to bind ICAM1 and EPCR were similarly expressed in isolates causing uncomplicated and cerebral malaria." (PMID 36419237, 2023). "Such P. falciparum cerebral malaria (CM) parasites express a subgroup of group A PfEMP1s that facilitate the dual binding to host intercellular adhesion molecule-1 (ICAM-1) and endothelial protein C receptor EPCR." (PMID 37630491, 2023).
cerebral malaria (continued). "Post-mortem immunohistochemical studies of cerebral malaria patients first showed ICAM-1 mediated adhesion of IEs to cerebral blood vessels." (PMID 36419237, 2023). "Postmortem studies have found that children who died from cerebral malaria had an upregulation of ICAM-1 on brain endothelial cells, which co-localized with infected erythrocytes." (PMID 36766633, 2023). "ICAM-1 is also expressed constitutively on monocytes, which are often present with the parasites at sites of cerebral micro-haemorrhages in cerebral malaria." (PMID 35379236, 2022). "ICAM1 is one the endothelial cell adhesion receptors for P. falciparum, but has a multifaceted role in cerebral malaria pathogenesis." (PMID 35787830, 2022). "Encoded by up to 60 variant genes, PfEMP1 binds to several host receptors including CD36 and the intercellular adhesion molecule 1 (ICAM1) and binding of infected erythrocytes to ICAM1 is implicated in the pathogenesis of cerebral malaria." (PMID 35222377, 2022). "The genetic polymorphism K29M in the immunoglobulin-like domain of ICAM-1, known as ICAM-1Kilifi, has been associated with either increased or decreased risk of developing cerebral malaria." (PMID 35379236, 2022). "Endothelial and epithelial ICAM-1 play pivotal roles in microbial pathogenesis, including the sequestration of P. falciparum-infected erythrocytes to endothelium in cerebral malaria, viral binding to epithelium and bacterial invasion." (PMID 35990682, 2022). "ICAM-1 was found to be up-regulated in endothelial cells and co-localized with iRBCs in brain tissue of children who died from cerebral malaria." (PMID 35379236, 2022). "The data obtained are indeed supportive of EPCR being an important endothelial receptor responsible for iRBCs binding in cerebral malaria cases, alongside ICAM‐1." (PMID 30804082, 2019). "More recently parasites causing cerebral malaria were shown to express var genes encoding for PfEMP1s that bind EPCR and ICAM‐1 in static binding assays." (PMID 30804082, 2019). "Nevertheless, the cytoadhesion predictions for CD36, EPCR, and ICAM-1 are supported by multiple in vitro studies of both laboratory-adapted P. falciparum lines (21, –, 23, 26, –, 28) and cerebral malaria isolates." (PMID 31040236, 2019). "An earlier study has reported that interaction with ICAM-1 contributes to increased serum TNF-α in cerebral malaria model of P. berghei ANKA-infected mice and that ICAM-1 deficient mice survive >15 days compared to 6–8 days in wild type (WT) mice." (PMID 30619355, 2018). "This discrepancy between the flow results and force spectroscopy findings led us to question the significance of ICAM-1 in contributing to sequestration in cerebral malaria." (PMID 28646215, 2017). "Expression of these PfEMP1s, predicted to bind both ICAM-1 and EPCR, is associated with increased risk of developing cerebral malaria." (PMID 28279348, 2017). "ICAM-1 upregulation is the only endothelial receptor known to have a positive correlation with cerebral malaria." (PMID 28646215, 2017). "Expression of these adhesion molecules on the cerebral microvascular endothelium has been reported in human and murine cerebral malaria and ICAM-1 GKO mice are protected against PbA-induced cerebral malaria." (PMID 25177551, 2014). "Further, co-localization of ICAM-1 with parasite sequestration in brain vessels in autopsy samples from cerebral malaria patients and up-regulation of ICAM-1 expression on endothelium during malaria infection was observed." (PMID 23446319, 2013). "ICAM-1 expressed on vascular endothelial cells has been suggested as a receptor involved in the development of cerebral malaria, a severe and often fatal complication with IE sequestration in the brain." (PMID 23936131, 2013). "In cerebral malaria correlation of increased local cellular expression of ICAM-1 with sequestration of infected parasites in the brain has been well demonstrated." (PMID 23866258, 2013).
cerebral malaria (continued). "The increased expression of membrane bound ICAM-1 followed by binding of parasites to it could therefore enhance sequestration of the parasites to cause vascular obstruction and ischaemia as postulated by the mechanical hypothesis of cerebral malaria development." (PMID 24386348, 2013). "Among the many host receptors, binding to Intercellular Adhesion Molecule -1 (ICAM-1) has been shown to be related to cerebral malaria." (PMID 22132804, 2011). "There is evidence to support ICAM-1 as a receptor for P. falciparum-infected erythrocytes and that it plays important roles in the pathogenesis of cerebral malaria." (PMID 22043276, 2011). "Previous studies have suggested a role for ICAM-1 in the pathology of cerebral malaria, although these have been inconclusive." (PMID 21390226, 2011). "Taken together, the published literature suggests that plasma ICAM-1 concentrations are higher in patients with more severe disease, but that levels cannot be used to distinguish children with cerebral malaria." (PMID 20712868, 2010). "Evidence for the role of cell-surface ICAM-1 expression in cerebral malaria comes from histologic studies." (PMID 20712868, 2010). "Almost all patient isolates bind to CD36, while the binding to ICAM-1 has widely different avidities among clinical isolates and is common among African patients with highest binding in cerebral malaria." (PMID 19650937, 2009). "Expression of ICAM-1 is upregulated on cerebrovascular endothelium, and P. falciparum IRBCs co-localize with ICAM-1 in cerebral vessels of patients who die of cerebral malaria, suggesting that adhesion to ICAM-1 plays a key role in cerebral sequestration." (PMID 17907801, 2007). "Binding to ICAM-1 has been established to be crucial and suspected to play an important role in cerebral malaria as it is involved in the selective accumulation of infected erythrocytes in the brains of cerebral malaria patients." (PMID 38093209, 2023). "Indeed, postmortem studies have demonstrated the upregulation of ICAM1 expression on the cerebral vascular endothelium in cerebral malaria." (PMID 35222377, 2022). "Several studies have provided evidence on the implication of the human host intercellular adhesion molecule-1 (ICAM-1) as a major receptor for iRBCs binding to P. falciparum erythrocyte membrane protein 1 (PfEMP1) in the development of severe and cerebral malaria." (PMID 35379236, 2022). "Importantly, antibodies against the DBLβ_motif inhibited ICAM-1-specific in vitro adhesion of erythrocytes infected by four of five P. falciparum isolates from cerebral malaria patients." (PMID 29426042, 2018). "IE adhesion to ICAM-1 has variously been associated with cerebral malaria, clinical but not severe malaria or inversely correlated with severe disease." (PMID 27149991, 2016). "There is a well-established link between adhesion of iRBCs to ICAM-1 and cerebral malaria." (PMID 26830671, 2016). "Moreover, administration of λ-carrageenan increases the expression of ICAM-1, which plays a key role in the sequestration of iRBCs in cerebral malaria under experimental and natural conditions." (PMID 25495520, 2014). "This may propose a role for ICAM-1 in the pathogenesis of cerebral malaria but additional studies are necessary to further validate this association." (PMID 24691798, 2014). "Thus, antibody levels to ICAM-1-selected parasites were lower during acute infection but increased significantly after recovery from both uncomplicated and cerebral malaria." (PMID 24386348, 2013). "The adhesion to ICAM-1 tended to be higher in patients with cerebral malaria." (PMID 23446319, 2013). "Both IFN-∼ and TNF-cl may play roles in dyserythropoietic anemia, and TNF-a may contribute to cerebral malaria as a result of up-regulation of intercellular adhesion molecule-1 (ICAM-1) in cerebral blood vessel endothelium." (PMID 22187584, 2011). "Among these host receptors, binding to ICAM-1 is related to cerebral malaria." (PMID 22132804, 2011).
cerebral malaria (continued). "In contrast, high expression of ICAM-1 on cerebral endothelial cells may contribute to cytoadhesion of parasitized red cells and cerebral malaria." (PMID 20712868, 2010). "Mouse models of cerebral malaria have supported the role of ICAM-1." (PMID 19680452, 2009). "Host genetic variation in ICAM-1 can lead to altered disease susceptibility and clinical outcome, including variant ICAM-1Kilifi which is associated with higher or sometimes in contradiction, decreased susceptibility to cerebral malaria in different geographical regions." (PMID 38093209, 2023). "However, a later study reported that ICAM-1 is dispensable for cerebral malaria pathogenesis." (PMID 30619355, 2018). "Indeed, IFN-γ and lymphotoxin α, the two key pathogenetic cytokines in experimental cerebral malaria, are strongly synergistic in inducing the expression of vascular cell adhesion molecule-1, intercellular adhesion molecule-1 (ICAM-1) and E-selectin in mouse brain endothelial cells in vitro." (PMID 25177551, 2014). "Up-regulation of ICAM-1 during infection and the possibility of its increased interaction with parasites expressing the appropriate corresponding PfEMP-1 phenotype may thus be important in the pathogenesis of cerebral malaria." (PMID 24386348, 2013). "This suggests that children who are protected from cerebral malaria have FcγRIIIb binding antibodies that target ICAM-1 binding DBLβ and which promote phagocytosis of ICAM-1 + EPCR binding IE by neutrophils." (PMID 39267089, 2024). "Further, phagocytosis of ICAM-1 + EPCR binding IE by THP-1 cells, which lack FcγRIIIa or b, was elevated in cerebral malaria." (PMID 39267089, 2024). "Expression of var genes containing the ICAM-1-binding motif, that are predicted to induce binding to ICAM-1 and EPCR, is thought to be involved in the pathogenesis of cerebral malaria." (PMID 36419237, 2023). "The link between ICAM-1 and EPCR to cerebral malaria symptoms has been established, but the mechanism of pathogenesis is still ambiguous." (PMID 35735506, 2022). "In experimental cerebral malaria reports, the use of rapamycin restricts the cytoadherence of infected RBCs on endothelial cells by VCAM-1 and ICAM-1 reduction." (PMID 35735506, 2022). "Recently, parasite strains able to bind both ICAM-1 and Endothelial Protein C Receptor (EPCR) have been isolated and characterized, strengthening the potential role of these two receptors in cerebral malaria." (PMID 35379236, 2022). "Histological examination of brains of patients who died of cerebral malaria have shown that iRBCs co-localized with ICAM-1 and binding to ICAM-1 was higher in children with cerebral malaria." (PMID 26830671, 2016). "Intercellular adhesion molecule 1 (ICAM-1) and the endothelial protein C receptor (EPCR) are candidate receptors for the deadly complication cerebral malaria." (PMID 27406562, 2016). "Some group A and B PfEMP1s can bind to intercellular adhesion molecule 1 (ICAM-1), and ICAM-1 expression was up-regulated in brain endothelium and co-localized with sequestered IEs in cerebral malaria patients." (PMID 27149991, 2016). "ICAM-1 and EPCR are candidate receptors for cerebral malaria, but there has been limited characterization of parasite lines with both adhesion traits." (PMID 27406562, 2016). "This suggests that the quality of the antibody response to dual ICAM-1 and EPCR binding PfEMP1 may be a more effective correlate of protection from cerebral malaria." (PMID 36419237, 2023). "An autopsy of a person with Pk malaria, but not with cerebral malaria (CM), demonstrated neither cytoadherence nor increased intercellular adhesion molecule 1 (ICAM-1) on brain endothelium." (PMID 37888606, 2023). "Moreover, the fungal ethanolic extract of Trichoderma stromaticum helps in reducing inflammation in experimental cerebral malaria by reducing the expression of VCAM-1 and ICAM-1, thus protecting the blood-brain barrier’s integrity." (PMID 35735506, 2022).
cerebral malaria (continued). "Further elucidation of the molecular determinants of PfEMP1–ICAM1 interaction and ability to predict ICAM1‐binding from the amino acid sequence is required to assess the role that group A PfEMP1 binding both ICAM1 and EPCR play in the pathogenesis of cerebral malaria." (PMID 27354391, 2016). "Furthermore, ICAM-1 expression by endothelial cells is enhanced by TNF-α and IL-1β, and ICAM-1 is important in cell adhesion, including adhesion of PRBC, in models of cerebral malaria." (PMID 23300448, 2012). "Monocyte ICAM-1 fluorescence was not different among those with cerebral malaria versus those without cerebral malaria." (PMID 20712868, 2010). "Patients suffering with cerebral malaria have up-regulated levels of ICAM-1 in the brain and parasite isolates from patients with malaria disease (including those with CM and compared to asymptomatic infection) showed higher binding to ICAM-1 protein." (PMID 19800372, 2010). "The 3D7 strain used in our study was selected for ICAM-1 and may not be an accurate representation of the interactions occurring in cerebral malaria." (PMID 28646215, 2017). "However, more studies linking ICAM‐1-adhering IEs to severe disease such as cerebral malaria and identifying ICAM-1-binding PfEMP1 epitopes (not least epitopes inducing adhesion-inhibitory antibodies) are needed before DBLβ3_D4 can be put forward as a vaccine candidate." (PMID 23936131, 2013). "One of the commonly used host receptors is ICAM-1, and it has been suggested that ICAM-1 has a role in cerebral malaria pathology, although the evidence to support this is not conclusive." (PMID 25360558, 2014). "Additionally, lack of TNF receptor 2 conferred resistance to cerebral malaria in mice, thought to be due to blocking the upregulatory effects of TNF on ICAM-1 expression in brain microvascular endothelial cells." (PMID 19680452, 2009).